CGA (glycoprotein hormones, alpha polypeptide)
Diseases named in the same sentence as CGA in open-access papers (continued):
Sharing a sentence is not in itself a finding about the gene and the disease.
tumor (continued). "This reflects that measurements are non-specific (10–35% specificity) because CgA is elevated in other neoplasias, e.g. pancreatic and small-cell lung neoplasias and prostate carcinomas, and can be raised by a variety of cardiac and inflammatory diseases as well as in renal failure." (PMID 25316294, 2014). "Of the 28 lymph nodes without histological tumor involvement, 14 had detectable CgA by PCR." (PMID 22720672, 2012). "However, as the clinical value of serum CgA and NSE are well established for neuroendocrine tumors (NETs), the elevation of these markers can also be observed in a number of other tumor types and benign diseases and therefore, do not appear as neuron-specific as considered previously." (PMID 22312308, 2012). "High CgA levels were observed in 19 of the 196 (10%) patients, which could not be explained by tumour recurrence or progressive disease." (PMID 21989216, 2011). "Levels of CgA tend to correlate with tumour bulk but not with symptoms." (PMID 17576444, 2006). "Immunocytochemical analysis revealed no NESP55 or CgA labelling in any of the tumours." (PMID 12771991, 2003). "Similarly, changes in CgA levels during treatment—particularly with somatostatin analogs or peptide receptor radionuclide therapy (PRRT)—have been proposed as surrogate markers of treatment response, but these remain unreliable and heavily dependent on tumor differentiation and secretory profile." (PMID 40869136, 2025). "Thus, many NEN assays which measure CgA do not define the neoplasm." (PMID 37444393, 2023). "However, some studies did not validate CgA as a surrogate marker for tumor progression of NETs." (PMID 34868938, 2021). "Therefore, we could not use repeated measurements of CgA to evaluate longitudinal change of CgA for tumor response prediction." (PMID 34868938, 2021). "Two monoanalytes, plasma chromogranin A (CgA) and urine 5-hydroxyindoleacetic acid (5HIAA) are used to monitor the course of these neoplasms during treatment of non-curable tumours, and may also have a role in detection of recurrence after potentially curative surgery or other treatments." (PMID 33244704, 2021). "Interestingly, there was no interrelationship between tumor CgA expression and serum CgA values." (PMID 30867449, 2019). "Finally, the bell-shaped dose-response curve and the consequent lack of PN1 induction by high concentrations of CgA may explain the lack of anti-tumor effects with high-dose CgA." (PMID 27683038, 2016). "This view is further supported by the results of contrast enhanced ultrasound analysis of tumors (CEUS), performed on a different group of mice, showing that treatment with 30 pmol of CgA (i.p.), but not 150 pmol, could significantly reduce the tumor perfusion index." (PMID 27683038, 2016). "Interestingly, 30 pmol CgA, but not 150 pmol (i.p.), could reduce bFGF in tumor tissue extracts, a proangiogenic cytokine." (PMID 27683038, 2016). "Furthermore, our study suggests the possible use of HIF1α expression as a better screening tool for the development of CRPC than other biomarkers of CRPC such as chromogranin A (CgA) or circulating tumor cells, because of its high sensitivity and negative predictive value." (PMID 23342109, 2013). "In conclusion, CgA and PP are not helpful in diagnosing panNETs in MEN1, not even in cases where tumor size exceeds 20 mm, the recommended cut-off for surgery." (PMID 40455177, 2025). "At immunocytochemistry, the tumor cells were positive for Syn, focally positive for galectin, TTF1, CDX2, thyroglobulin, and negative for Ct and CgA." (PMID 40542625, 2025). "Most studies have demonstrated that tumor cells express S-100, CD68, and Vimentin, whereas markers such as CK, Syn, CgA, Desmin, and pituitary hormones are typical negative, with the majority of cases also showing negativity for GFAP." (PMID 40860841, 2025). "The tumor cells were positive for CKpan and CK7, while being negative for CgA, Syn, thyroid transcription factor-1 (TTF-1), P63, and P40." (PMID 38335397, 2024).
tumor (continued). "The tumor cells were negative expression of epithelial markers, including PCK, EMA, CK8/18, CK20 and low molecular weight keratin (CAM5.2), as well as CgA, CD56, S100, HMB45, CD117, DOG1, CD99, WTI, Desmin and SMA." (PMID 38877473, 2024). "Tumor cells in the epithelial and mesenchymal regions DOG-1, CD34, S-100, SOX-10, STAT 6, SMA, desmin, Syn, and CgA were negative; SDHB-positive expression; Ki-67 proliferation index was 3%." (PMID 37658451, 2023). "The posterior mediastinal tumor was examined only by biopsy and was diagnosed as NET G2, and was positive for CgA and serotonin but negative for gastrin." (PMID 37867522, 2023). "CgA is highly expressed in well-differentiated NEN and therefore the concentration does not necessarily reflect the aggressiveness of the tumor." (PMID 37318593, 2023). "The tumor displays diffuse positivity for SYP, somatostatin, and the less consistently positive or absent CgA." (PMID 36830839, 2023). "The tumor cells were negative for AE1/3, Cam5.2, CKIT, DOG1, CD99, SOX10, S100, HMB45, MelanA, Syn, CgA, Trypsin, Desmin, SMA, Caldesmon, collagen type 4, Laminin, Inhibin, Calretinin, STAT6, CD34, ERG, WT1, ER, PR, and SALL4." (PMID 36928336, 2023). "Immunohistochemistry showed that tumor cells consistently and diffusely expressed CD99, and expressed Vimentin, Syn and NSE to varying degrees, while CgA a.nd S-100 were often negative." (PMID 36626543, 2022). "In G3 patients, CgA, CD56, Ki-67, CD24, CD44 and laminin were highly expressed in tumour tissue relative to that in non-tumour tissue with the exception of CD24 for one patient." (PMID 36362433, 2022). "In G2 patients, with the exception of Ki-67 in one patient, CgA, CD56, Ki-67, CD31 and vimentin were more highly expressed in tumour tissue relative to that in non-tumour tissue." (PMID 36362433, 2022). "F-PNET, Chromogranin A (CgA) ≥200pmol/L, high Ki67 index, G3-NEC, lymph node positivity, and tumor stage IV were significant negative predictors of OS." (PMID 35837305, 2022). "Although few immune-related genes had a high expression in cold tumor, such as MMP8, most genes highly express in cold tumor are not so closely related to immune responses, including CGA, INHA, IBSP, and CHRNA9." (PMID 33816503, 2021). "Other factors (age and gender, location of primary tumour, surgical resection of primary tumour, presence of extrahepatic metastases, SSTR uptake, baseline levels of CgA or urinary 5-HIAA) did not appear to be predictive of response to treatment." (PMID 31556004, 2020). "Immunohistochemical staining showed that the tumour cells expressed TTF1, napsin A, and CK7, but not P63, P40, CK5/6, CgA, Syn, CD56, and TG." (PMID 33282636, 2020). "The tumor cells were positive for CD99, FLI1 and EMA, but negative for CD3, CgA, CD20, CKpan, S100 and HMB45." (PMID 25780425, 2015). "On the other hand, tumor cells stained negative for CK20, transcription termination factor 1 (TTF-1), melanoma antibody (HMB45) and CgA." (PMID 24884973, 2014). "Immunohistochemically, the tumor cells were strong positive for CD56, CD3ε, TIA1, and weak positive for LMP1, and negative for CD5, CD8, CD20, CD79a, CgA, Syn, SCLC, CK, EMA, CD99, CD10, TdT, PAX-5, and BCL-6." (PMID 23958352, 2013). "Nevertheless the number of cases stained by the neuroendocrine markers of Syn, CgA, S-100 and NSE, and myoepithelial markers of desmin was limited, no positive finding in all tumor cells was still a meaningful result." (PMID 23587094, 2013).
tumor (continued). "In the histopathological examination, mediastinal NET G1 was diagnosed, without necrosis, mitotic activity 0/2 mm2, immunophenotype CgA (+), CD56 (+), Ki 67 1%, CK AE1/AE3 (+), CD117 (+), p40 (-), TdT (-), PAX8 (-), and the presence of tumor cell embolism in the vessels." (PMID 40071083, 2025). "Elevated CgA has limited specificity and is not recommended for routine monitoring in MTC but may reflect tumor burden in select cases." (PMID 40869471, 2025). "Immunohistochemically, tumor cells were positive for AE1/AE3 cytokeratin, EMA (cytoplasmic pattern), and TTF-1 (nuclear pattern), and were negative to neuroendocrine markers (CgA and Syn) and S100." (PMID 39851953, 2025). "The tumor cells are positive for ACTH, CgA, CD56, but negative for insulin and gastrin." (PMID 36830839, 2023). "The outlier samples that did not fit in the overall pattern seen within each grade included CgA and CD56 in Grade 1 which were lower in Patient 1 relative to that in non-tumour tissue, while the other G1 tissues were higher in the tumour tissues relative to those in the non-tumour tissue." (PMID 36362433, 2022). "Furthermore, the circulating concentration of CgA fragments, such as WE-1, EL35 and GE-25, has been found to be increased in patients with PPGLs, but its biological activity and utility as tumor markers have not been addressed." (PMID 34201922, 2021). "Tumor cells of case No. 2 were positive for AE1/AE3, CK7, calretinin, D2-40, focal positive for WT-1, and negative for HMB45, Melan-A, Desmin, S100, Syn, CgA, CD31, and CD34." (PMID 34248850, 2021). "Interestingly, well-established histology or serum-based parameters of tumor aggressiveness or burden, such as the proliferation index Ki67 (PFS, p = 0.09) or CgA (OS, p = 0.06), failed to reach prognostic significance." (PMID 27705948, 2017). "In cancer patients, elevated CgA and NSE levels correlates with tumor burden, number of dissemination sites, and lack of clinical response, while a decrease of these biomarkers might indicate a better prognosis." (PMID 28194370, 2017). "Staining of tumor tissue sections with an anti-CD31 antibody (a marker of endothelial cells) at day 14 showed that 30 pmol, but not 150 pmol of CgA, could significantly reduce vascular density." (PMID 27683038, 2016). "To date, the use of either single-specific tumor products (e.g. serotonin, PP, and neuron specific enolase (NSE)) or a general marker of neuroendocrine secretion (CgA) has not met the rigorous criteria to be considered optimally effective in attaining these goals." (PMID 25316294, 2014). "Furthermore, the lack reaction of Syn, CgA, S-100, NSE, CD34, and Desmin supported the origin of tumor cells from pulmonary epithelium, rather than neuroendocrine, vascular-endothelium, or myoepithelium." (PMID 23587094, 2013). "Furthermore, CgA, rather than SPP1, serves as an indicator of tumor aggressiveness." (PMID 38835066, 2024).
cancer (56 papers, 1995 to 2025). A tumor composed of atypical neoplastic, often pleomorphic cells that invade other tissues. "CgA cleavage was observed also with cultured human monocyte-derived macrophages or with cancer-associated fibroblasts derived from PDAC." (PMID 33425767, 2020). "Additionally, HuR inhibition reduces the levels of glycoprotein hormones, alpha polypeptide (CGA), a marker associated with hormone-induced tumors, suggesting a potential use of Eltrombopag in treatment of cancers overexpressing CGA." (PMID 39849491, 2025). "A growing body of evidence suggests that CgA is more than a diagnostic marker for cancer patients." (PMID 22529895, 2012). "We investigated 92 putative cancer‐related plasma proteins including chromogranin A (CgA) and clinical parameters at the time of diagnosis to identify early factors associated with progressive (PD) or stable disease (SD)." (PMID 40812788, 2025). "Both GB-NETs and carcinomas exhibit gastric/intestinal metaplasia and CgA-positive cells, suggesting a potential common precursor lesion." (PMID 40589647, 2025). "This method enabled the detection of CgA in artificial saliva samples with a detection threshold of 0.11 μg/ml, showing promise for future clinical applications in cancer patients." (PMID 38835066, 2024). "Whereas chromogranins, including CgA-negative ones, are important, CgA is the most commonly used granin in clinical practice, especially as CgB-positive cancers become more prevalent." (PMID 37568540, 2023). "Remarkably, CgA cleavage predicts progression-free survival and overall survival in these cancer patients." (PMID 36559048, 2022). "Baseline CgA was a statistically significant prognostic marker for both cancer-specific survival (CSS) and progression-free survival (PFS)." (PMID 33244704, 2021). "To investigate the role of cancer cells on CgA fragmentation we incubated recombinant CgA1-439 in the presence or absence of various human PDAC cell lines (Hs766T, MiaPaCa-2, BxPC-3, A8184, PT45, and PaCa44 cells) or murine Panc02 cells." (PMID 33425767, 2020). "The CgA system, comprising full‐length CgA and its fragments, is emerging as an important player in cardiovascular, immunometabolic, and cancer regulation." (PMID 31588572, 2019). "Overall, the CgA system, consisting of full‐length CgA and its fragments, is emerging as an important and complex player in cardiovascular, immunometabolic, and cancer regulation." (PMID 31588572, 2019). "It is increasingly clear that inflammatory diseases and cancers are influenced by cleavage products of the pro-hormone chromogranin A (CgA), such as the 21-amino acids long catestatin (CST)." (PMID 30337922, 2018). "Chromogranin A (CgA), a neuroendocrine secretory protein, and its fragments are present in variable amounts in the blood of normal subjects and cancer patients." (PMID 27683038, 2016). "CgA staining was observed in a minority of cancer cells, approximately 10%, in the form of secretory granuli." (PMID 19956567, 2009). "This is a preliminary report on pS2 expression in prostate cancer, a larger study will better define the correlation between stage, grade of cancer with pS2 and CgA expression." (PMID 15588310, 2004). "Our results have similarly shown that 6 out of 9 cancers that have expressed pS2 were also positive for CgA." (PMID 15588310, 2004). "The aim of the present study was to use ARM to explore and discover combinations of cancer‐related human plasma proteins, CgA, and clinical factors at the time of diagnosis in patients with siNET or pNET and progressive disease or stable disease within 3 years of follow‐up." (PMID 40812788, 2025). "Additionally, these carcinomas frequently express neuroendocrine markers, most notably Syn, CgA, CD56 and NF." (PMID 38668799, 2024). "However, we found that among the DEGs, one of the genes most strongly upregulated in response to L3MBTL2 knockdown was a hormone-related gene (CGA), whose role in cancer is still unclear." (PMID 35521536, 2022).
cancer (continued). "Therefore, we will argue against the routine use of plasma CgA measurement in patients with GI symptoms, flushing-like symptoms, or unspecific cancer symptoms." (PMID 33138020, 2020). "Using specific assays, we recently observed that CgA is present in the blood of normal subjects and cancer patients as a mixture of full-length protein and fragments, including the N-terminal fragment CgA1-76 (vasostatin-1) and other fragments lacking part or the entire C-terminal region." (PMID 27683038, 2016). "Thus, variable levels of full-length CgA and fragments are present in the blood of cancer patients for a variety of reasons." (PMID 27683038, 2016). "Pathophysiological changes in CgA blood levels and/or its fragmentation might regulate disease progression in cancer patients." (PMID 27683038, 2016). "Five cases were CgA and serotonin positive; three of these carcinomas were also positive for HDC." (PMID 22474435, 2012). "All carcinomas (12 out of 12) were strongly positive for CgA." (PMID 12771991, 2003). "Here, we review the structural requirements for the interactions of CgA and CgA-fragments with neuropilin-1 and integrins, their biological effects, their mechanisms, and the potential use of compounds targeting these ligand-receptor interactions for cancer diagnosis and therapy." (PMID 36559048, 2022). "In addition to non-cancer disease, many other factors may interfere with the CgA level, such as food and drugs." (PMID 34868938, 2021). "However, partial degradation was observed after 3 h of incubation, suggesting that also these cells may contribute to CgA degradation, although less efficiently than cancer cells." (PMID 33425767, 2020). "Monitoring CgA and vasostatin‐1 levels in cancer patients before and after doxorubicin therapy, the administration of low‐dose full‐length CgA to patients with low CgA levels might represent a novel approach to prevent doxorubicin‐induced cardiotoxicity, thereby meriting further investigation." (PMID 31588572, 2019). "Moreover, elevated plasma CgA levels may occur in a variety of conditions unrelated to the presence of a malignant tumor." (PMID 29232390, 2017). "Therefore, in this study we evaluated, in cancer patients, the temporal relationships between the increases in plasma CgA and urinary 5-hydroxyindoleacetic acid (5-HIAA) and the development of vomiting following dacarbazine, nitrogen mustard and cyclophosphamide treatments." (PMID 7547218, 1995). "Many of these DEGs, including CGA, CDKN1A, FN1, CLIC3, and S100P, have been reported to play essential roles in cancer progression." (PMID 35521536, 2022). "HSP prevented BON cancer cell proliferation and induced cancer cell death by decreasing achaete-scute complex-like 1(ASCL1), chromogranin A (CgA), and enhanced Notch 1 expression." (PMID 35128104, 2022). "In eight large cell NE carcinomas or carcinomas with large cell components, INSM1 showed similar sensitivity (6/8) to SNY (7/8), CgA (6/8) and CD56 (6/8)." (PMID 34943408, 2021). "The markers (SYP, CGA, and INSM1) were evaluated with both pure primary pancreatic NET and mixed adenoneuroendocrine carcinoma (MiNEN, which contains both NET and carcinoma components)." (PMID 34943408, 2021). "NCI-H82 and PC-3 cancer cells are highly aggressive human cell lines which, as we show in the present study, express high levels of NE markers NSE and CgA as well as the AVP receptor V2." (PMID 28194370, 2017). "Western blot analysis revealed that treatment of NE cancer cells with TDP-A changed the NE phenotype in all three cell lines and led to dose-dependent decrease in the expression of ASCL1, SYN and CgA." (PMID 29050323, 2017). "Clear cell carcinoid of lung: These clear cancer cells are diffuse positive for Syn, CgA, NSE, cytokeratin, and so on, as well as negative for HMB-45, Malen-A, CD34, and so on." (PMID 36800595, 2023).